FFAR2 (free fatty acid receptor 2)
Description:
G protein-coupled receptor that is activated by a major product of dietary fiber digestion, the short chain fatty acids (SCFAs), and that plays a role in the regulation of whole-body energy homeostasis and in intestinal immunity. In omnivorous mammals, the short chain fatty acids acetate, propionate and butyrate are produced primarily by the gut microbiome that metabolizes dietary fibers. SCFAs serve as a source of energy but also act as signaling molecules. That G protein-coupled receptor is probably coupled to the pertussis toxin-sensitive, G(i/o)-alpha family of G proteins but also to the Gq family. Its activation results in the formation of inositol 1,4,5-trisphosphate, the mobilization of intracellular calcium, the phosphorylation of the MAPK3/ERK1 and MAPK1/ERK2 kinases and the inhibition of intracellular cAMP accumulation. May play a role in glucose homeostasis by regulating the secretion of GLP-1, in response to short-chain fatty acids accumulating in the intestine. May also regulate the production of LEP/Leptin, a hormone acting on the central nervous system to inhibit food intake. Finally, may also regulate whole-body energy homeostasis through adipogenesis regulating both differentiation and lipid storage of adipocytes. In parallel to its role in energy homeostasis, may also mediate the activation of the inflammatory and immune responses by SCFA in the intestine, regulating the rapid production of chemokines and cytokines. May also play a role in the resolution of the inflammatory response and control chemotaxis in neutrophils. In addition to SCFAs, may also be activated by the extracellular lectin FCN1 in a process leading to activation of monocytes and inducing the secretion of interleukin-8/IL-8 in response to the presence of microbes. Among SCFAs, the fatty acids containing less than 6 carbons, the most potent activators are probably acetate, propionate and butyrate. Exhibits a SCFA-independent constitutive G protein-coupled receptor activity.
Synonyms: GPR43; FFA2R
Tractability: Small molecule: a drug acting on it is in phase 2 or 3 trials; a structure with a bound ligand is known; a high-quality ligand is known; it belongs to a druggable protein family. Antibody: UniProt places it where antibodies can reach, with high confidence; its Gene Ontology location is reachable by antibodies, with high confidence; UniProt predicts a signal peptide or a membrane-spanning region. PROTAC: a small molecule that binds it is known.
Target class: Family A G protein-coupled receptor; Small molecule receptor (family A GPCR); Membrane receptor; Free fatty acid receptor; Lipid-like ligand receptor (family A GPCR)
Chemical probes: GLPG-0974 (high quality)
Gene: Protein-coding gene on chromosome 19 (35,443,907 to 35,451,767, forward strand). Ensembl gene ENSG00000126262.
Subcellular location: Cell membrane
Pathways (Reactome):
Signal Transduction: Free fatty acid receptors; G alpha (q) signalling events
Gene Ontology:
Molecular function: G protein-coupled receptor activity; protein binding
Biological process: cell surface pattern recognition receptor signaling pathway; cellular response to fatty acid; G protein-coupled receptor signaling pathway; positive regulation of interleukin-8 production; fat cell differentiation; glucose homeostasis; leukocyte chemotaxis involved in inflammatory response; lipid storage; mucosal immune response; positive regulation of acute inflammatory response to non-antigenic stimulus; positive regulation of chemokine production; positive regulation of cytokine production involved in immune response; regulation of acute inflammatory response; regulation of peptide hormone secretion; phospholipase C-activating G protein-coupled receptor signaling pathway
Cellular component: plasma membrane; membrane
Genetic constraint (gnomAD): Loss-of-function variants: 0 observed, 1.01 expected, observed/expected ratio (o/e) 0, 90% interval 0 to 1.72. That is too few expected variants to judge how well the gene tolerates losing a copy. Missense variants: 421 observed, 450.93 expected, observed/expected ratio (o/e) 0.93, 90% interval 0.86 to 1.01. Synonymous variants: 193 observed, 198.06 expected, observed/expected ratio (o/e) 0.97, 90% interval 0.87 to 1.1.
Homologues: Orthologues: chimpanzee FFAR2 (99% identical), macaque FFAR2 (97% identical), rat Ffar2 (85% identical), mouse Ffar2 (85% identical), pig FFAR2 (83% identical), dog FFAR2 (82% identical), guinea pig FFAR2 (82% identical), rabbit FFAR2 (81% identical), tropical clawed frog ffar2 (47% identical), zebrafish si:dkey-211g8.6 (43% identical), zebrafish si:ch73-90p23.1 (42% identical), zebrafish si:dkey-211g8.7 (35% identical). Paralogues in human: GPR42 (38% identical), FFAR3 (38% identical), FFAR1 (25% identical), P2RY2 (23% identical), P2RY4 (22% identical), P2RY6 (22% identical), P2RY1 (21% identical), HCAR3 (20% identical), HCAR2 (20% identical), OXGR1 (20% identical), SUCNR1 (20% identical), OXER1 (19% identical), and 3 more.
Diseases named in the same sentence as FFAR2 in open-access papers:
FFAR2 is named in the same sentence as 170 diseases in open-access papers, as found by Europe PMC text mining. Sharing a sentence is not in itself a finding about the gene and the disease. The quoted sentences say what the papers report.
colitis (141 papers, 2012 to 2026). Inflammation of the colon. "This has been validated in FFAR2-deficient mice that show an exacerbated or unresolved inflammation in experimentally induced colitis." (PMID 36977462, 2023). "Nonetheless, FFAR2-deficient mice (Gpr43−/−) showed exacerbated or unresolving inflammation in models of colitis, arthritis, and asthma and increased alveolar bone resorption." (PMID 35320973, 2022). "Activation of FFAR2 inhibited colitis and inflammation, while mice deficient in FFAR2 showed a severe inflammatory response in colitis that was related to an increase in the recruitment of immune cells." (PMID 36144406, 2022). "FFAR2 deficient dendritic cells lead to exacerbated colitis by controlling excessive IL-27." (PMID 34572293, 2021). "On the other hand, butyrate activates GPR43 (FFAR2) to promote the proliferation of colonic mucosal T regulatory cells (Tregs), thereby helping to suppress experimental colitis." (PMID 41450947, 2025). "It is crucial to acknowledge the findings of previous research, which have demonstrated that FFAR2−/− mice display more severe symptoms of colitis." (PMID 38721154, 2024). "In this regard, acute DSS colitis in conventional C57BL/6 mice decreased the expression of Ffar2, Ffar3, and Hcar2, although this result was not confirmed by others." (PMID 38595917, 2024). "GPCR43 (FFAR2) knockout mice showed exaggerated or unresolved inflammation in murine models of arthritis, asthma and colitis with increased production of pro-inflammatory cytokines." (PMID 38255274, 2024). "The activation of FFAR2 by SCFAs has been demonstrated to exert anti-inflammatory properties and to confer protection against experimental colitis." (PMID 38675452, 2024). "SCFAs also regulate the size and function of the colonic Treg pool and prevent colitis in mice in a Ffar2(GPR43)-dependent manner." (PMID 38903520, 2024). "Loss of function studies in mice have demonstrated that the mouse ortholog Ffar2/Gpr43 and Ffar3/Gpr41 receptors participate to intestinal homeostasis by regulating inflammation in response to chemically induced colitis." (PMID 38177905, 2024). "Animal studies have shown that SCFAs can regulate the size and function of the colonic Treg pool and protect against colitis in a Ffar2 (GPR43)-dependent manner in mice." (PMID 38403666, 2024). "Another sub-strain, Lactis BL-99, promotes up-regulation of acetate and butyrate receptors, including FFAR2, FFAR3 and GPR109a expression, which negatively correlates with monocytes and macrophages and ameliorates colitis-associated lung injury in mice." (PMID 38110878, 2023). "Other authors also confirmed this data treating WT mice with an FFAR2 agonist, and they observed a reduction in DSS-induced colitis compared with controls, indicating that FFAR2 activation plays a key role in the protection of intestinal inflammation." (PMID 33897470, 2021). "In a previous study, FFAR2 was shown to be an important regulator of inflammation in a mouse model of colitis." (PMID 34074061, 2021). "They showed a significant difference in the p38 phosphorylation in neutrophils from WT mice compared with FFAR2 KO mice in DSS-induced colitis." (PMID 33897470, 2021). "These evidence shows FFAR3 signaling similar to FFAR2 is a promising therapeutic target for treating gut related disorders such as obesity, T2D, colitis and diarrhea, by honing gut-hormonal synthesis and balancing the microbiome-gut-brain axis." (PMID 32521775, 2020). "This has been found to be the case in T regulatory cells in the colon, where FFAR2 activity protects against colitis." (PMID 33304273, 2020). "On the other hand, FFAR2 KO mice with chronic DSS-induced colitis phenotype shows a decrease in invasion of PMNs and cytokine keratinocyte chemoattractant synthesis as compared to wild-type (WT) mice." (PMID 32521775, 2020). "Many of the inflammatory cytokines attenuated by FFAR2 and FFAR3, including C5, CCL1, CCL2, GM-CSF, IL-1α, IL-1β, ICAM-1 and TNF, are associated with colitis." (PMID 27667443, 2016).
colitis (continued). "In mice, SCFAs regulate the size and function of the colonic regulatory T-cell (Treg) pool and protect against colitis in an Ffar2-dependent manner." (PMID 27094081, 2016). "In addition, it has been reported that SCFAs also can increase colonic Treg population size and function and protect against colitis in a Ffar2(GPR43)-dependent manner." (PMID 39546084, 2025). "Colitis was induced by the delivery of 3% DSS for 7 days in FFAR2/3 KO mice." (PMID 39057718, 2024). "Indeed, stimulation of FFAR2 by SCFAs was necessary to resolve inflammation in models of colitis, arthritis, and asthma." (PMID 36797287, 2023). "FFAR2-knockout mice exhibited aggravation in colitis, arthritis, asthma and glucose tolerance." (PMID 37959133, 2023). "Also, propionate was shown to enhance Treg function in an FFAR2-dependent manner, protecting mice from colitis." (PMID 36977462, 2023). "Moreover, FFAR2 knock-out (KO) mice show more severe inflammation in colitis, arthritis, and airway inflammatory (asthma) in mice, which indicates that FFAR2 signaling helps in reducing the proinflammatory response." (PMID 32521775, 2020). "Moreover, activation of FFAR2 by SCFAs ameliorates colitis in chronic dextran sodium sulphate (DSS)-induced colitis mice model." (PMID 32521775, 2020). "Further investigations to determine: (i) if FFAR2 or FFAR3 signalling is altered in the monocytes of colitis patients, and (ii) whether this abnormality is involved in disease pathology– may reveal novel insights on colitis and its treatment." (PMID 27667443, 2016). "In addition, SCFAs regulate the size and function of the colonic pool of regulatory T cells and protect against colitis in a FFAR2-dependent manner in mice." (PMID 25875123, 2015). "Gut microbiota and FFAR2 regulate inflammatory responses in colitis." (PMID 25875123, 2015). "Additionally, colitis severity was similar in FFAR2/3 KO and WT mice after DSS application." (PMID 39057718, 2024). "Taken together with the upregulation of GPR43-encoding Ffar2 mRNA among the SCFA-sensing GPCRs, it raises the possibility that GPR43 might be involved in the propionate-mediated anti-inflammatory functions through RORγthigh-ILC3s in experimental colitis." (PMID 35720414, 2022). "However, the role of GPR43/FFAR2 on colitis is still controversial." (PMID 26140540, 2015). "To elucidate the involvement of the SCFA receptors, FFAR2 and FFAR3, in DSS-induced colitis, we repeated the DSS experiments in dual FFAR2/3 knockout mice." (PMID 39057718, 2024). "Dietary fiber generates SCFAs that act on GPCRs in immune and non-immune cells, where propionic, acetic, and butyric acids boost colonic regulatory T-cell (Treg) activity by activating GPCR FFAR2 (GPCR43), thereby reducing colitis in mice." (PMID 36817063, 2022). "These two FAs decreased the inflammatory response in macrophages mediated via FFAR1, FFAR2, FFAR3, and AMPK; attenuated the development of colitis; and were involved in the elimination of C. glabrata from the gut." (PMID 36144406, 2022). "Contrary outcomes were presented by two other research groups whose investigations showed that FFAR2 KO mice were preserved against DSS and 2,4,6-trinitrobenzenesulfonic acid solution (TNBS)-induced colitis." (PMID 34444876, 2021). "To investigate the possible synergistic anti-inflammatory effect of a MOR agonist DAMGO and a FFAR2 antagonist GLPG 0974 in the mouse GI tract, we used a well-known mouse model of colitis induced by DSS which mimics UC." (PMID 34833919, 2021). "Knockout mice studies implicate the mammalian short-chain fatty acid (SCFA) receptors, FFAR2 and FFAR3– in colitis, arthritis and asthma." (PMID 27667443, 2016). "The potential involvement of monocyte FFAR2 and FFAR3 in human colitis, through the modulation of these cytokines, is therefore conceivable." (PMID 27667443, 2016). "Moreover, we observed that during DSS-induced colitis, expression of FFAR1 was significantly increased, while FFAR2 decreased in the colon." (PMID 34444876, 2021).
colitis (continued). "Widespread expression of FFAR2/3 make them play an important role in several human diseases such as type 1 and type 2 diabetes, obesity, inflammatory bowel disease (IBD), Crohn’s disease, cardiovascular diseases, gout, asthma, arthritis, and colitis." (PMID 32521775, 2020). "We investigated whether the SCFA-FFAR2/3-GLP-1 pathway is important for protection against intestinal disease utilising dual-receptor FFAR2/3 KO mice treated with DSS for 7 days and hypothesised that FFAR2/3 KO mice would present with severe colitis." (PMID 39057718, 2024). "Furthermore, we observed a robust increase in FFAR1 expression, with no apparent change in FFAR2–4 during TNBS-induced colitis." (PMID 34444876, 2021). "Further studies with the experimental models of colitis and arthritis, have demonstrated that SCFAs could bind the GPR43 (G protein-coupled receptor 43, also known as free fatty acid receptor 2, FFAR2) and thus repressing the inflammation via interaction with FFAR2-expressing neutrophils." (PMID 28061847, 2017). "Expression of FFAR2 on immune cells seems to be important in the regulation of immune responses, since mice lacking FFAR2 develop exacerbated inflammation in models for colitis, asthma, and arthritis due to higher production of inflammatory mediators and increased recruitment of immune cells." (PMID 23914191, 2013). "Importantly, Ffar2 modulation did not affect lymphocytes of adaptive immunity, nor ILC1 or ILC2, but potentiated ILC3 proliferation and IL-22 production as the basis for the mechanism of action for the observed protective effect of Cpd1 against colitis and Citrobacter rodentium infection." (PMID 38238790, 2024).
Obesity (110 papers, 2012 to 2026). Accumulation of substantial excess body fat. "Several reports indicate that FFA2 receptor deficiency entails obesity, while FFAR2 overexpression in adipose tissue protects mice from obesity even under high-fat diets." (PMID 33578942, 2021). "Obesity is frequently observed in FFAR2-deficient mice on a normal diet, while overexpressed FFAR2 in adipose tissue mice remain lean, even though the mice are fed a high-fat diet." (PMID 26999199, 2016). "On the other hand, the fact that Ffar2 (GPR43)-deficient (Ffar2-KO) mice are completely protected from high-fat diet-induced obesity, dyslipidemia, and fatty liver supports the importance of SCFAs/GPR43 signaling in the development of NAFLD." (PMID 27682116, 2015). "Ffar2-deficient mice were shown to exhibit obesity, whereas mice overexpressing adipose-specific Ffar2 overexpressed mice exhibited leanness under normal conditions." (PMID 25875123, 2015). "In this study, we found that the source of FFAR2 ligands was dependent on gut microbes, because Ffar2 deficiency induced obesity in mice, whereas mice overexpressing Ffar2 only in adipose tissues exhibited leanness under normal conditions." (PMID 25414667, 2014). "Another study showed that protective effects of the dietary fiber inulin on HFD-induced obesity is preserved in FFAR2-deficient mice or mice receiving β-acids that decrease bacterial-derived SCFAs, indicating an FFAR2- and SCFA-independent mechanism of protection." (PMID 33578942, 2021). "Starting from an early embryonic stage, maternal gut microbiota-SCFA-FFAR2 signaling plays a crucial role in regulating metabolic syndrome, as FFAR2 KO mice embryos have lower insulin and higher glucose level, and are more susceptible to obesity and diabetes in adulthood." (PMID 32521775, 2020). "From a translational perspective, these findings suggest that dietary fiber supplementation, or strategies that mimic its effects on microbiota and myeloid FFAR2 activation, may provide novel approaches to mitigate somatosensory dysfunction associated with obesity and Western diet consumption." (PMID 41282164, 2025). "SCFA-mediated FFAR2/3 signaling plays crucial roles in glucose and lipid metabolic pathways, and a few studies showcasing perturbed FFAR2 expression in mice underscore the important association between SCFA and cardiometabolic risk in models of obesity." (PMID 36678142, 2023). "Further, transgenic mice with overexpression of FFAR2 specifically from adipocytes were protected against HFD-induced obesity and insulin resistance." (PMID 36678142, 2023). "Several in vitro studies have contributed to what we know regarding the influence of SCFA-activated FFAR2/3 on adipocyte metabolic regulation, informing the roles of SCFAs in the onset and progression of obesity." (PMID 36678142, 2023). "In contrast, the effects of FFAR2 on GLP-1 and PYY levels shed light on the therapeutic value of FFAR2 pharmacological targeting for diabetes, obesity, and other metabolic disorders." (PMID 35328722, 2022). "One study of knockout mice has indicated that FFAR2 plays a major role in mediating the effect of gut microbiota on host obesity and immunity." (PMID 36092902, 2022). "FFAR2 and FFAR3 have also been associated with inflammation and metabolic diseases such as diabetes and obesity." (PMID 36404915, 2022). "Further evidence for a protective role of FFAR2 signaling in the context of energy metabolism comes from a study that showed beneficial effects of fermentable carbohydrates on food intake and obesity." (PMID 33578942, 2021). "Either through genetic mutational study on FFAR2/3 or their interactive action with targeted agonists and antagonists would help in exploring the exact mechanism of action of FFAR2/3 against various gut hormonal comorbidities such as obesity and T2D." (PMID 32521775, 2020). "It has been shown that HFD-fed Ffar2 knockout mice exhibited obesity correlated with high expressed mRNA level of PPAR-γ in abdominal fat tissues." (PMID 32756446, 2020).